GPR3 (G protein-coupled receptor 3)
Description:
Constitutively active G protein-coupled receptor that maintains high cAMP levels and contributes to several processes, including meiotic arrest in oocytes and neuronal development, through activation of intracellular signaling pathways. Essential activator of thermogenic adipocytes, where it drives thermogenesis via constitutive G(s)-coupling activity in the absence of ligand. May be activated by lipid-derived agonists such as oleoylethanolamide (OEA), oleic acid or sphingosine 1-phosphate leading to activation of the G(s)/cAMP/PKA signaling pathway. Plays a potential role in modulating brain functions, including behavioral responses to stress and amyloid-beta peptide generation in neurons (By similarity). Stimulates neurite outgrowth in cerebellar granule neurons via PKA, ERK, and PI3K-mediated signaling pathways (By similarity).
Synonyms: ACCA
Tractability: Small molecule: a structure with a bound ligand is known; it belongs to a druggable protein family. Antibody: its Gene Ontology location is reachable by antibodies, with high confidence; UniProt places it where antibodies can reach, with medium confidence; UniProt predicts a signal peptide or a membrane-spanning region. PROTAC: a small molecule that binds it is known.
Target class: Family A G protein-coupled receptor; Membrane receptor
Gene: Protein-coding gene on chromosome 1 (27,392,622 to 27,395,814, forward strand). Ensembl gene ENSG00000181773.
Subcellular location: Cell membrane
Gene Ontology:
Molecular function: protein binding; G protein-coupled receptor activity; sphingosine-1-phosphate receptor activity
Biological process: adenylate cyclase-activating G protein-coupled receptor signaling pathway; positive regulation of cold-induced thermogenesis; G protein-coupled receptor signaling pathway; sphingosine-1-phosphate receptor signaling pathway
Cellular component: cytoplasm; plasma membrane; membrane
Genetic constraint (gnomAD): Loss-of-function variants: 16 observed, 17.28 expected, observed/expected ratio (o/e) 0.93, 90% interval 0.63 to 1.4. The upper end of that interval is the gene's LOEUF score, 1.4, which puts it in group 5 of 6, group 1 being the genes least tolerant of losing a copy. Missense variants: 326 observed, 431.3 expected, observed/expected ratio (o/e) 0.76, 90% interval 0.69 to 0.83. Synonymous variants: 183 observed, 190.22 expected, observed/expected ratio (o/e) 0.96, 90% interval 0.85 to 1.09.
Homologues: Orthologues: chimpanzee GPR3 (99% identical), macaque GPR3 (99% identical), dog GPR3 (97% identical), rabbit GPR3 (96% identical), pig GPR3 (95% identical), guinea pig GPR3 (94% identical), mouse Gpr3 (94% identical), rat Gpr3 (93% identical). Paralogues in human: GPR6 (58% identical), GPR12 (56% identical), S1PR5 (31% identical), LPAR2 (27% identical), LPAR3 (25% identical), S1PR1 (25% identical), S1PR2 (25% identical), S1PR4 (25% identical), S1PR3 (24% identical), LPAR1 (24% identical), MC5R (24% identical), CNR1 (24% identical), and 6 more.
Diseases named in the same sentence as GPR3 in open-access papers:
GPR3 is named in the same sentence as 32 diseases in open-access papers, as found by Europe PMC text mining. Sharing a sentence is not in itself a finding about the gene and the disease. The quoted sentences say what the papers report.
Anxiety (6 papers, 2009 to 2025). Intense feelings of nervousness, tension, or panic often arise in response to interpersonal stresses. "Another study demonstrated that GPR3-/- mice exhibited higher levels of anxiety-associated behavior in the elevated plus maze and depression-like behavior in the forced swim and tail suspension tests." (PMID 40866560, 2025). "Two brain-specific Gαs coupled orphan receptors that have recently been associated with anxiety- and depression-like behaviors, are GPR3 and GPR26." (PMID 33589739, 2022). "To investigate whether their anxiety-like behavior was associated with aggressiveness, we evaluated Gpr3−/− mice in the resident-intruder test." (PMID 19259266, 2009). "There are some orphan GPCRs which are highly expressed in the PFC and that have been associated with anxiety- and depression-like traits, such as GPR158, GPR56, GPR3, and GPR26." (PMID 33589739, 2022). "Together these results suggested that Gpr3−/− mice displayed increased behavioral inhibition in a stressful novel environment, indicating an altered response to stressful events and/or an anxiety-like phenotype." (PMID 19259266, 2009). "RTI-19318-32 was further validated as being selective for GPR3, as it did not alter nicotine intake in GPR3 knockout mice, nor did it exert effects on anxiety-associated behavior or locomotion." (PMID 40866560, 2025). "With respect to stress and anxiety, we identified Glp1r, which directly interacts with the HPA axis to trigger the secretion of glucocorticoids and Gpr3 which modulates anxiety- and depressive-related behaviors by regulating monoaminergic neurotransmitters and their metabolites." (PMID 37228107, 2023). "Another G-protein coupled receptor upregulated in the EE pigs, GPR3, has been shown to be involved in anxiety related behaviours, with Gpr3-/- mice displaying increased anxiety-like behaviours that could be rescued with the use of the anxiolytic diazepam." (PMID 29778628, 2018). "Identification of the endogenous ligand(s) of GPR3 or agents capable of modulating its constitutive activity is expected to open new therapeutic avenues in the treatments of disorders affecting mood or anxiety." (PMID 19259266, 2009). "Together, these findings indicate that the GPR3 agonist does not alter general locomotor or anxiety-associated behaviors, although it may affect feeding-related behavior at the higher, but not lower, dose." (PMID 40866560, 2025). "For instance, the GPR3 agonist would be predicted to decrease anxiety- and depression-like behaviors based on this prior study, which could make the agonist an even more attractive target for nicotine therapeutics, as nicotine use is often associated with anxiety and depression in humans." (PMID 40866560, 2025). "However, Gpr3−/− mice exhibited a higher level of anxiety-related responses after exposure to unfamiliar stressful environment in the open-field and the elevated plus-maze paradigms, including a behavioral inhibition observed as a reduced activity in the open-field test." (PMID 19259266, 2009). "Control behavioral analysis further supported the selectivity of GPR3 agonist action, with no off-target effects of RTI-19318-32 on general locomotor behavior and anxiety-associated behavior." (PMID 40866560, 2025).
Obesity (6 papers, 2015 to 2024). Accumulation of substantial excess body fat. "Beyond its involvement in the nervous system, GPR3 is also associated with energy consumption and obesity." (PMID 38287117, 2024). "Most recently, mice deficient in GPR3 were shown to develop late-onset obesity and GPR3 regulates thermogenesis in adipocytes, suggesting a role of GPR3 in regulating metabolism." (PMID 38280848, 2024). "DPI significantly inhibits HFD-induced weight gains without affecting food intake, consistent with the development of late-onset of obesity in Gpr3−/− mice and Pkm2−/− mice." (PMID 38280848, 2024). "In this study, we have investigated the effect of GPR3 activation by DPI on the metabolic reprogramming of macrophages, the underlying molecular mechanisms, and the physiological effect on HFD-induced obesity and liver pathogenesis." (PMID 38280848, 2024). "The highly constitutive Gs coupling activity of GPR3 in thermogenic adipocytes is a desirable trait for energy expenditure and metabolic regulation, especially in the context of obesity and other metabolic disorders." (PMID 38287117, 2024). "In mice, GPR3 activation in Kupffer cells results in enhanced glycolysis, reduced inflammation and inhibition of high-fat diet induced obesity and liver pathogenesis." (PMID 38280848, 2024). "There were no genotypic differences in thermogenic gene expression or propensity to develop HFD-induced obesity, suggesting that the global KO phenotypes originated from GPR3 in another tissue than BAT." (PMID 34048700, 2021). "In order to better understand why GPR3 KO mice develop obesity later in life we performed additional studies on 5-month-old (adult) animals, as this was the latest time point before the obese phenotype became apparent." (PMID 26455425, 2015). "Furthermore, G-protein-coupled receptor 3 (GPR3), which is associated with energy expenditure and obesity, is an attractive target for the treatment of metabolic disorders such as obesity and diabetes." (PMID 38501107, 2024). "Here we report an unexpected link between aging and obesity via GPR3." (PMID 26455425, 2015). "GPR3 may, therefore, serve as a new pharmacological target in the development of relevant therapeutic intervention to treat obesity in the aging population." (PMID 26455425, 2015). "Mice lacking GPR3 display late-onset obesity associated with a reduction in uncoupling protein 1 protein level in iBAT and thermogenesis." (PMID 26455425, 2015). "Here, we show that activation of G-protein coupled receptor 3 (GPR3) in Kupffer cells stimulates glycolysis and protects mice from obesity and fatty liver disease." (PMID 38280848, 2024). "Here we report for the first time that male mice lacking GPR3 display late-onset obesity when maintained on regular chow diet." (PMID 26455425, 2015).
Alzheimer disease (5 papers, 2011 to 2026). A progressive, neurodegenerative disease characterized by loss of function and death of nerve cells in several areas of the brain leading to loss of cognitive function such as memory and language. "Taken together, these results suggest an important role of the allosteric sodium binding site for GPR3 activity and open a possible avenue for the modulation of Aβ production in the Alzheimer’s Disease." (PMID 30038319, 2018). "The overexpression of GPR3 in neurons increases amyloid-beta production, which is pathologically deposited in Alzheimer's disease." (PMID 22216338, 2011). "GPR3 belongs to the protein superfamily of G protein-coupled receptors (GPCRs) and plays a central role in both benign and malignant physiological processes, such as energy expenditure in adipocytes and Alzheimer's disease pathology, respectively." (PMID 42096618, 2026). "The discovery that GPR3, GPR6, and GPR12 are molecular targets for CBD provided important mechanistic insight for understanding the therapeutic potential of CBD for various diseases, including Alzheimer’s disease and Parkinson’s disease." (PMID 39404382, 2024). "GPR3, GPR6, and GPR12 are expressed in various areas of the brain and peripheral tissues, where they play important roles in pathological conditions such as Alzheimer’s disease, Parkinson’s disease, addiction, obesity, and cancer." (PMID 39404382, 2024). "S1P, as an agonist on GPR3, GPR6, GPR12, may be a promising target in Alzheimer’s Disease." (PMID 38895631, 2024).
depression (5 papers, 2009 to 2025). "Finally, we observed a differential expression of iRNAPII-BRs and nearby genes—ADRB2, CXCL8, SFN, and GPR3—in major depressive disorder, indicating that iRNAPII-BR-associated transcription may contribute to the pathophysiology of this disorder." (PMID 41446805, 2025). "GPR3 regulates both serotonergic and dopaminergic synthesis; thus, targeting this receptor with an agonist would maintain 5-HT and dopamine at normal levels and improve depression and aggressive behaviour." (PMID 32102186, 2020). "Indeed Gpr3−/− mice exhibited a behavioral despair as evidenced by an increased duration of immobility in the tail suspension and the forced swim tests, which are widely used to assess the efficacy of antidepressant drugs and genetic manipulation relevant to depression." (PMID 19259266, 2009).
breast carcinoma (2 papers, 2021 to 2022). "For GPR3, its agonists may render the breast cancer cells susceptible to cytotoxicity induced by cationic amphiphilic drugs, leading to lysosomal-dependent cell death, which showed the tumor-suppressive effect." (PMID 35463319, 2022). "It was previously shown in breast cancer stem cells that decreased G-protein-coupled receptor 3, of which CBD is an inverse agonist, increased the expression of NANOG, which could explain the increase in NANOG in response to CBD." (PMID 34832951, 2021).
medulloblastoma (2 papers, 2009 to 2018). A malignant, invasive embryonal neoplasm arising from the cerebellum. "Cell cycle kinetics of GPR3-transfected medulloblastoma cells revealed a G0/G1 block, consistent with cell cycle exit." (PMID 19526062, 2009). "In 2012 a general consensus was reached regarding the existence of only four molecular subgroups of medulloblastomas, termed WNT, SHH, Group 3 (GPR3), and Group 4 (GPR4)." (PMID 30279357, 2018). "The frequency of medulloblastoma patients in these four groups were 34% for GPR4, 28% for SHH, 27% for GPR3, and 11% for WNT." (PMID 30279357, 2018). "Finally to provide further evidence for effects of GPR3 on cell cycle kinetics, DAOY medulloblastoma cells were transfected with control or GPR3 expressing vector." (PMID 19526062, 2009).
premature ovarian failure (2 papers, 2023 to 2025). "The resumption of meiosis would be activated after GPR3 knockout and causes premature ovarian failure." (PMID 36938502, 2023).
colorectal cancer (1 paper, 2026). A primary or metastatic malignant neoplasm that affects the colon or rectum. "Clostridium butyricum inhibits METTL3 expression in colorectal cancer cells by upregulating G protein-coupled receptor 3 (GPR3), leading to the downregulation of vimentin and vascular endothelial growth factor receptor 2 (VEGFR2)." (PMID 41602751, 2026).
Hyperglycemia (1 paper, 2015). An increased concentration of glucose in the blood. "Ablation of GPR3 did not cause systemic hyperglycemia, hyperinsulinemia, dyslipidemia, liver damage or alteration of major of metabolic markers under non-fasting conditions." (PMID 26455425, 2015).
melanoma (1 paper, 2021). A malignant, usually aggressive tumor composed of atypical, neoplastic melanocytes. "Taken together, these data demonstrate an inverse expression between two miRNAs (MIR211-5p and MIR328-3p) and two targeted mRNAs (AURKB and GPR3) that toggles concurrently with the transition of arrested melanocytic nevi to melanomas." (PMID 34812139, 2021). "The expression of both AURKB and GPR3 protein and mRNA was enriched in melanomas as compared to nevi." (PMID 34812139, 2021).
metabolic syndrome (1 paper, 2015). A cluster of metabolic risk factors for CARDIOVASCULAR DISEASES and TYPE 2 DIABETES MELLITUS. "In spite of being overweight, the metabolic profile of 12-month old GPR3 KO mice did not display classic systemic features of the metabolic syndrome." (PMID 26455425, 2015).
metastatic disease (1 paper, 2018). "At diagnosis, 24% of patients have a metastatic disease and the highest frequency of metastatic disease was observed among GPR3 and GPR4." (PMID 30279357, 2018).
multiple sclerosis (1 paper, 2011). A progressive autoimmune disorder affecting the central nervous system resulting in demyelination. "Further studies are needed to better understand the roles of these receptors in multiple sclerosis and its treatment and to clarify the utility of GPR3 and IL17RC expression levels in the blood as markers of long-term prognosis." (PMID 22216338, 2011).
neuropathic pain (1 paper, 2021). Chronic pain caused by damage to nerve fibers. "In addition, the GPR3 alters emotional behaviour, participates in the development of neuropathic pain and regulates morphine‐induced antinociception." (PMID 34418142, 2021).
nicotine dependence (1 paper, 2020). Physical and psychological dependence on nicotine. "This signaling leads to the possibility that α3 * nAChR may be regulated by cAMP, the level of which is increased via GPR3, and this mechanism may be involved in nicotine dependence." (PMID 33253222, 2020).
ovarian failure (1 paper, 2021). "Although GPR3 is expressed in the human oocyte, it contributes nothing to premature ovarian failure, which is unlike the phenotype of GPR3 KO mice." (PMID 33842483, 2021).
Zinc deficiency (1 paper, 2024). A deficiency of the essential metal Zinc; an essential cofactor for many enzymes. "Through RT-qPCR analysis, we observed a significant increase in the mRNA level of Gpr3, while the expression levels of Star and Cyplla1 were markedly reduced in zinc deficiency mice." (PMID 38807213, 2024).
metabolic disease (6 papers, 2021 to 2025). A congenital disorder (due to inherited enzyme abnormality) or acquired (due to failure of a metabolically important organ) disorder resulting from an abnormal metabolic process. "Given the potential of GPR3 in neurodegenerative diseases and metabolic disorders, we sought to solve the structure of GPR3 in complex with Gs protein by cryo-electron microscopy (cryo-EM)." (PMID 38287117, 2024). "The orphan G protein-coupled receptor (oGPCR) GPR3 representsapotential drug target for the treatment of Alzheimer’s diseaseand metabolic disorders." (PMID 37907069, 2023). "These prior findings support the notion that GPR3 may be a possible target for treating metabolic disease, especially considering that in humans, higher levels of GPR3 expression in brown adipose tissue was correlated with a lower body mass index." (PMID 40866560, 2025). "Gpr3 expression is physiologically induced in thermogenic adipocytes by cold exposure, and mimicking this event through overexpression in mice is fully sufficient to increase energy expenditure and counteract metabolic disease." (PMID 41173363, 2025). "Consequently, increasing Gpr3 expression in thermogenic adipocytes is alone sufficient to drive energy expenditure and counteract metabolic disease in mice." (PMID 34048700, 2021). "Thus, GPR3 overexpression in thermogenic adipocytes completely protects mice from the development of metabolic disease." (PMID 34048700, 2021). "Our genetic gain-of-function studies suggested that GPR3 may hold therapeutic potential for metabolic disease." (PMID 34048700, 2021).
cancer (2 papers, 2023 to 2024). A tumor composed of atypical neoplastic, often pleomorphic cells that invade other tissues. "Many of these genes, such as VIM, FOSL2, PTN, GPR3, SIAH2, UPP1, S100A2 are associated with cell migration and epithelial-mesenchymal transition (EMT) in several cancers." (PMID 36850002, 2023).
neurodegenerative disease (2 papers, 2024). A disorder of the central nervous system characterized by gradual and progressive loss of neural tissue and neurologic function. "Molecules targeting GPR3, GPR6 and GPR12 are of interest for therapeutic applications since they are implicated in several neurodegenerative diseases, including AD, PD, HD and MS." (PMID 38895631, 2024). "Despite the promising roles of GPR3, GPR6, and GPR12 in neurodegenerative diseases, including AD, further research is required to fully elucidate their mechanisms of action and validate them as viable therapeutic targets." (PMID 38895631, 2024).
kidney (1 paper, 2022). "Many of these genes have been shown to be associated with steady-state, heat tolerance and renal function; for example, EXOC3 maintains organ homeostasis by driving lipid metabolism, FGR causes kidney injury, GPR3 is a receptor gene involved in adipose thermogenesis and MLX regulates metabolism." (PMID 36552284, 2022).
GPR3 also shares sentences with these, for which no sentence is quoted: glioma (2 papers); Neurological Disease (2); tumor (2); Creutzfeldt Jakob disease (1); diabetes (1); epilepsy (1); fatty liver disease (1); Glucose intolerance (1); Hyperinsulinemia (1); Parkinson disease (1); Perrault syndrome with (1).